RNU6-309P (RNA, U6 small nuclear 309, pseudogene)
Gene: Small nuclear RNA gene on chromosome X (108,826,764 to 108,826,869, forward strand). Ensembl gene ENSG00000201443.
Homologues: Orthologues: chimpanzee U6 (99% identical), macaque U6 (96% identical), pig U6 (68% identical). Paralogues in human: RNU6-753P (83% identical), RNU6-20P (82% identical), RNU6-211P (82% identical), RNU6-653P (82% identical), RNU6-820P (82% identical), RNU6-961P (82% identical), RNU6-1316P (81% identical), RNU6-310P (81% identical), RNU6-761P (81% identical), RNU6-812P (81% identical), RNU6-1031P (80% identical), RNU6-1048P (80% identical), and 1287 more.